TERT (telomerase reverse transcriptase)
Diseases named in the same sentence as TERT in open-access papers (continued):
Sharing a sentence is not in itself a finding about the gene and the disease.
medulloblastoma (continued). "However, a significant association between TERT promoter mutations and outcomes was noted in SHH and Group 4 medulloblastomas." (PMID 24174164, 2013). "Thus, we conclude that TERT mutations define distinct prognostic patient cohorts in a subgroup-specific fashion with good prognosis in SHH and poor prognosis in Group 4 medulloblastomas." (PMID 24174164, 2013). "TERT mutations in both WNT and SHH medulloblastomas were positively correlated with age." (PMID 24174164, 2013). "As TERT mutations are predominantly observed in non-infant medulloblastomas, we evaluated the prognostic implications of these promoter mutations across all four medulloblastoma subgroups in an age-dependent manner." (PMID 24174164, 2013). "Notably, only 1/6 (17 %) of TERT-mutated WNT tumors harbored monosomy 6, while this alteration is observed in approximately 80 % of TERT wild-type medulloblastomas of the WNT subgroup (p = 0.005)." (PMID 24174164, 2013). "We demonstrate that TERT promoter mutations comprise the most recurrent mutation in adult SHH tumors identified to date and potentially define distinct prognostic subgroups in SHH and Group 4 medulloblastoma patients." (PMID 24174164, 2013). "However, the clinical and biological implications of TERT mutations in medulloblastoma have not been described." (PMID 24174164, 2013). "We now demonstrate that SHH tumors with TERT mutations are mostly mutually exclusive with those harboring 10q loss (p = 0.017) Notably, the relatively favorable prognosis of TERT-mutated SHH medulloblastomas may be explained by the relative lack of high-risk biomarkers." (PMID 24174164, 2013).
acral melanoma (17 papers, 2017 to 2026). "The punctuated formation of complex aberrations and early TERT activation suggest a unique mutational mechanism that initiates acral melanoma." (PMID 39034322, 2024). "TERT promoter mutations are associated with poorer survival and higher metastatic rate in both UV-related and acral melanomas." (PMID 37239381, 2023). "TERT promoter mutations were found in 4 cases (13%): two acral lentiginous melanomas also harbored a BRAF mutation, another a NRAS mutation, while a nodular melanoma harbored a NF1 mutation." (PMID 33917086, 2021). "However, a retrospective study of Chinese patients with acral melanoma showed that TERT promoter mutations were present in only ~5% of cases." (PMID 34149718, 2021). "A recent study showed TERT protein expression in half of the primary acral lentiginous melanomas and all metastatic melanomas with variable percentages and intensities." (PMID 40361989, 2025). "TERT amplifications were reported in 23% of acral-lentiginous melanomas and less than 5% in desmoplastic melanomas." (PMID 29751586, 2018). "All acral melanomas displaying TERT copy number gains were also all BRAF wild type, but overlapped with N/KRAS and NF1 alterations." (PMID 29156643, 2017). "Our observation that genomic alterations of TERT are a common and early event in acral melanoma would support the notion that hailstorms result from telomere crisis as they ceased to form at later progression stages at which telomerase was already genetically activated." (PMID 39034322, 2024). "Recurrent non-V600E BRAF, KIT, NF1, and TERT promoter mutations, present in acral melanoma, were not identified." (PMID 30995742, 2019). "By contrast, acral melanomas are more often driven by high amplitude amplifications of CCND1, CDK4, MDM2, and TERT, among other genes." (PMID 39034322, 2024). "Aberrations in MAPK, PI3K/AKT/PTEN, TERT, WNT, and CDK4/CDKN2A signaling pathways are frequent in acral melanoma." (PMID 34149718, 2021). "Alterations of RAS pathway members are also very frequent in acral melanomas, being detected in 87% of these patients: NRAS (17%), Aurora Kinase A (AURKA) (37.5%), Ciclin D1 (CCND1) or telomerase reverse transcriptase (TERT, 31%), and RAS (25%)." (PMID 29156643, 2017). "There are several mutations occurring in acral melanoma that we did not identify in acral naevi, including NF1, KIT, and TERT promoter alterations, recently reported in 15%, 12%, and 11% of acral melanomas, respectively." (PMID 30995742, 2019). "Longer telomeres in acral melanoma could indicate that TERT activation was not selected by critically short telomeres but to re-cap the ends of broken chromosomes of cells that had not yet exhausted their telomeres." (PMID 39034322, 2024). "Also, TERT amplifications may represent a poor prognostic marker in breast and urothelial bladder carcinomas, NSCLC, and acral-lentiginous melanoma." (PMID 29751586, 2018). "In addition, acral melanoma frequently exhibits complex structural alterations, including amplifications and deletions of chromosomes, particularly affecting the cyclin D1 (CCND1), cyclin-dependent kinase 4 (CDK4), and telomerase reverse transcriptase (TERT) genes." (PMID 39202970, 2024).
head and neck cancer (17 papers, 2015 to 2025). A primary or metastatic malignant neoplasm affecting the head and neck. "The study aimed to evaluate TERT promoter (TERTp) mutations in tumor DNA extracted from oral rinses as potential biomarkers for head and neck cancers." (PMID 41487579, 2025). "In contrast, Asian patients with head and neck cancer (HNC) harbored more TERT promoter mutations compared to White patients (OR = 2.47; 95%CI, 1.39-4.37; P = .004)." (PMID 37462445, 2024). "In HPV-related cancers, TERT gene is always expressed in cells infected by high risk HPVs at diverse body sites, such as cervix, vulva, vagina, anus, penis and head-and-neck cancers." (PMID 35804458, 2022). "The applicability of the telomerase reverse transcriptase (TERT) gene Rs2736100 polymorphism in cancer research has been well documented for various malignancies except for head and neck cancers, where data is sparse." (PMID 36415512, 2022). "Similarly, mutation of TERT also serves as a prognostic factor for head and neck cancer which reduces the efficacy of cisplatin treatment." (PMID 36715825, 2023). "To date, no studies have evaluated these mutations in the Brazilian population, therefore the aim of the present study was to evaluate the prevalence of TERT promoter mutations in head and neck cancer patients in Brazil and evaluate for associations with outcome." (PMID 32850388, 2020). "We conclude that CCND1, AXL, CDKN2A, TERT, and EZH2 are the hub genes involved in cisplatin resistance in head and neck cancer that have significant mRNA expression and effect on overall survival." (PMID 36715825, 2023). "As a proof of principle, integrated analysis of copy number variation, exome and transcriptome of 4 head and neck cancer cell lines and TCGA HNSCC dataset identify NRBP1, UBR5, ZNF384 and TERT as novel candidate oncogenes in HNSCC." (PMID 26572163, 2015).
diabetes (16 papers, 2018 to 2025). "It was found that parental clinical manifestation of diabetes is significantly associated with shorter telomeres, TERT gene polymorphism and up-regulation of the immune senescence markers, especially the KLRG1 in newborns." (PMID 41168774, 2025). "Previous reports indicate that the over expression of TERT is associated with the pathogenesis of diabetes, rheumatoid arthritis, and systemic lupus erythematosus." (PMID 38783329, 2024). "The possible mechanism whereby Par-4 mediates islet β cell apoptosis in diabetes likely involves an association with the TERT and Akt signalling pathway." (PMID 30186877, 2018). "Furthermore, genotypic analysis revealed a predominance of the C/C genotype of TERT (rs2736100), which showed significant associations with diabetes [10 (50%)] and hypertension [9 (56%)] (p = 0.001)." (PMID 41168774, 2025). "However, a study found that TERT allele homozygotes had a lower prevalence of diabetes than heterozygotes (5.63% vs. 15.38%, p = 0.039)." (PMID 41168774, 2025). "TERT encodes telomerase reverse transcriptase, which contributes to stem cell self-renewal and is downregulated in senescent adipose tissue-derived MSCs from obese pigs or patients with diabetes." (PMID 37231414, 2023). "The ARIC study of 15,792 IS patients revealed an association between TERT gene polymorphisms and IS risk among African Americans, but found that this relationship was weaker when the regression model incorporated hypertension, diabetes, BMI, and smoking history in the regression model." (PMID 39180127, 2024). "Therefore, loss of TERT expression (e.g. in diabetes or aging) may accompany insulin sensitivity and glucose uptake." (PMID 29938393, 2018). "This study is the first to report TERC (rs10936599) and TERT (rs2736100) gene variations in parents and their newborns, revealing that the homozygous C/C genotype is prevalent in chronic diseases like diabetes and hypertension." (PMID 41168774, 2025). "Diabetes has been shown to increase the methylation of TERT in the kidney and COL1A1 in the skin, leading to reduced expression of these genes and expedited aging." (PMID 39296334, 2024). "The suggested mechanism proposes that diabetes expedites aging processes through the hypermethylation of TERT and COL1A1 promoters." (PMID 39296334, 2024). "Our findings indicate that, in the periodic group, the methylation levels of TERT in the kidney and whole blood incrementally increased as diabetes progressed." (PMID 39296334, 2024). "In individuals with diabetes, this hypermethylation tends to reduce TERT expression, consequently leading to the shortening of telomeres and impairing DNA repair mechanisms, exacerbated by the elevated levels of ROS induced by diabetes." (PMID 39296334, 2024). "To elucidate the impact of diabetes on gene expression in the kidney and skin, we examined the expressions of TERT and COL1A1." (PMID 39296334, 2024). "Supplementation with soybean extract increased the amount of TERT and restored telomerase function resulting in an increase in the number of pancreatic β‐cells in diabetes‐induced rats." (PMID 38455184, 2023). "The relationship between arterial hypertension, diabetes mellitus and ischemic diseases, and TERT SNPs were studied." (PMID 36359275, 2022). "The present study showed a decreased prevalence of diabetes in homozygotes of the rs2736100 SNP of the TERT gene (5.63% vs. 94.37%, p = 0.039)." (PMID 36359275, 2022). "This prospective, observational study aimed to investigate the relationship between single nucleotide polymorphisms (SNPs) of TERT and the severity of OSA, taking into account hypertension and diabetes prevalence." (PMID 36359275, 2022). "Our findings suggest the following: first, diabetes induces Par-4 and inhibits TERT expression and decreases their interaction, promoting islet β cell apoptosis, whereas inhibition of Par-4 relieves apoptosis, as previous studies have indicated." (PMID 30186877, 2018).
diabetes (continued). "TERT overexpression has an antiapoptotic effect on islet β cells, providing a novel target for the treatment of diabetes." (PMID 30186877, 2018). "We show that Par-4 has an inhibitory effect on TERT and Akt to induce apoptosis of islet β cells in the pathology of diabetes." (PMID 30186877, 2018). "Our findings suggest that diabetes triggers enhanced methylation of the TERT and COL1A1 promoters." (PMID 39296334, 2024). "This study explored the polymorphic alleles of TERC and TERT gene in parents-newborn (triad) and its association with telomere length (TL) and parental diseases (mother: Gestational Diabetes Mellitus (GDM), Preeclampsia, fathers: Diabetes, Hypertension)." (PMID 38192544, 2024). "However, SNPs of the TERT gene (rs2736100 and rs2853669) were found to affect arterial hypertension and diabetes prevalence." (PMID 36359275, 2022). "Moreover, a lower prevalence of diabetes was observed in homozygotes of rs2736100 TERT than in heterozygotes (5.63% vs. 15.38%, p = 0.039)." (PMID 36359275, 2022). "Some studies have indicated that Par-4 interacts with TERT to regulate the cell apoptosis, but whether the interaction between Par-4 and TERT is involved in islet β cell apoptosis in diabetes remains unknown." (PMID 30186877, 2018). "It has been also postulated that TERT overexpression could induce cell survival and therefore to be applied to ease diabetes mellitus and its vascular complications." (PMID 29938393, 2018). "Therefore, this study aimed to associate the polymorphisms of telomerase gene (TERC and TERT) in parents-newborn (triad) with telomere length and parental diseases (mother: Gestational Diabetes Mellitus(GDM) and preeclampsia, fathers: Diabetes and Hypertension)." (PMID 38192544, 2024). "Furthermore, TERT expression is decreased in diabetes, leading to the question of whether this decreased TERT level meets the requirement for Par-4 inhibition and results in the translocation of Par-4 to the nucleus to induce apoptosis." (PMID 30186877, 2018). "Inactivation of telomerase (TERT) in adipocyte progenitor cells (APC) expedites telomere attrition, and the onset of diabetes in mice fed high‐fat diet (HFD), which promotes APC over‐proliferation and replicative senescence." (PMID 39932851, 2025). "Analysis of the TERC and TERT genes revealed a high frequency of the CC genotype in newborns of parents with chronic diseases, particularly diabetes [ TERC: 16 (79%)] (p = 0.079), TERT: 10(50%) (p = 0.00)]." (PMID 41168774, 2025). "In this study, TERT and COL1A1 were utilized as markers to evaluate the implications of diabetes on aging." (PMID 39296334, 2024). "In this study, we elucidate the modulatory influence of diabetes on the aging process, focusing specifically on the modifications in TERT in the kidney and COL1A1 in the skin using mice of Swiss Webster strain as the diabetes model." (PMID 39296334, 2024). "Therefore, this study aimed to evaluate the role of TERT SNPs (rs2736100 and rs2853669) in OSA, taking into account hypertension and diabetes prevalence." (PMID 36359275, 2022). "The observed alterations in the methylation levels of TERT and COL1A1 propound the hypothesis that diabetes potentially expedites the aging process, concomitantly impinging on the production of TERT and COL1A, ostensibly through the mechanism of promoter gene hypermethylation." (PMID 39296334, 2024). "Our findings reveal a marked impact of diabetes on the methylation statuses of TERT and COL1A1, characterized by an elevation in methylation levels within the periodic group (1st–6th week) and a simultaneous, progressive attenuation in the expression of TERT and COL1A1 genes." (PMID 39296334, 2024). "However, existing methodologies primarily focus on whole-genome methylation; the mechanisms of COL1A1 and TERT in diabetes-induced aging are not entirely understood." (PMID 39296334, 2024).
diabetes (continued). "Also, some confounding factors, such as patient comorbidities (in our study most common comorbidities were included in statistical analysis such as HTA and diabetes mellitus) and relevant molecular markers (e.g., BRAF, RAS, TERT, etc.), could have had an impact on the results." (PMID 39767178, 2024).
lymphoma (16 papers, 2010 to 2023). A malignant (clonal) proliferation of B- lymphocytes or T- lymphocytes which involves the lymph nodes, bone marrow and/or extranodal sites. "TERT encodes the catalytic subunit of telomerase, which has been shown to be upregulated in 90% of different types of human cancers surveyed, including lymphomas." (PMID 29439385, 2018). "Apart from regulating Myc stability, TERT can also be recruited to Myc target promoters in Myc-driven lymphoma cells probably through association with Myc." (PMID 28184371, 2017). "We sought to investigate whether TERT promoter mutations play a role in TERT activation in human lymphomas." (PMID 27792139, 2016). "We show that TERT regulation of miRNAs alters Bcl-2 and an enriched pathway associated with the dysregulated genes is chronic myeloid leukemia, which has overlapping genes with some of the lymphomas previously studied." (PMID 27627813, 2016). "The present study investigates the influence of ALV integration on the TERT promoter region methylation status at the site of integration in ALV-induced lymphoma." (PMID 29439385, 2018). "In contrast, there was a complete lack of detectable methylation in the ALV LTRs of proviruses in the TERT promoter region in lymphomas." (PMID 29439385, 2018). "Important insights about the interplay between Myc and TERT have been derived using a mouse model of lymphomagenesis in which lymphoma is specifically driven by Myc." (PMID 28184371, 2017). "This study suggests the existence of a feed-forward loop between Myc and TERT in Myc-driven cancers like lymphoma, wherein Myc upregulates TERT transcription and TERT, in turn, stabilizes Myc protein levels to promote lymphomagenesis." (PMID 28184371, 2017). "Our lab has repeatedly observed TERT activation in chicken lymphomas via ALV integration into the chTERT promoter region as an early event in avian B-cell lymphomagenesis." (PMID 27792139, 2016). "While B-lymphosarcoma cells are tumor cells that express TERT due to chromosomal translocations." (PMID 36910209, 2023). "Thus, we studied the epigenetic state of the ALV provirus and the TERT promoter in chicken lymphomas with clonally expanded TERT promoter integrations." (PMID 29439385, 2018). "Furthermore, chickens with TERT promoter integrations represent a subset of a larger collection of ALV-induced lymphomas." (PMID 29439385, 2018). "However, as TERT inhibition was found to select activation of ALT pathways in lymphoma, combined drugs that suppress telomerase and ALT-pathway could be beneficial to minimize emergence of resistance." (PMID 36291091, 2022). "In line with this assumption, we observed high rates of TMM-associated mutations in brain, liver, bladder, and kidney tumors and TERT expression despite lack of TMM-associated mutations in lymphomas, tumors of the gastrointestinal tract, and female reproductive system." (PMID 32024817, 2020). "Previous studies have shown common integration sites in ALV-induced lymphomas near MYC, MYB, BIC and, more recently, the telomerase reverse transcriptase (TERT) genes." (PMID 29439385, 2018). "The influence of ALV integration on the methylation of the chicken TERT promoter has not been characterized previously in ALV-induced lymphomas." (PMID 29439385, 2018). "It was shown that vTR contributes to the rapid onset of lymphoma formation by serving as a template for TERT, but it also has functions that are independent of the telomerase complex." (PMID 22046133, 2011).